PHB2 (prohibitin 2)
Diseases named in the same sentence as PHB2 in open-access papers (continued):
Sharing a sentence is not in itself a finding about the gene and the disease.
tumor (35 papers, 2009 to 2026). "Conversely, PHB2 inhibits cyclin-dependent kinase inhibitors (CKIs), such as p21 and p27, further enhancing cell cycle progression and reducing tumor cell susceptibility to DNA damage-induced apoptosis." (PMID 40076502, 2025). "Furthermore, the TOMM20 can facilitate ROS-induced pyroptosis and PHB2 is associated with apoptosis, indicating the interaction and coexistence of different programmed cell death as tumor grows." (PMID 35692054, 2022). "Specifically, PHB2 upregulates Cyclin D1 and Cyclin E, facilitating G1/S phase transition and promoting uncontrolled tumor cell proliferation." (PMID 40076502, 2025). "Co-immunoprecipitation showed that GOLPH3 acted as a scaffold to recruit LC3-II and prohibitin-2 to trigger autophagy and tumour progression." (PMID 40293576, 2025). "To further investigate the role of PHB2 in vivo, we established MKN-28.sh-PHB2 sublines with stable shRNA knockdown of PHB2 expression and investigated tumour growth in nu/nu mice." (PMID 38200519, 2024). "Three potential binding proteins, including YBX1, YBX2 and PHB2, were selected for further validation considering their molecular weights, protein scores, subcellular localizations and potential involvement in tumour metastasis and progression." (PMID 37929660, 2024). "Functionally, silencing PHB2 in GC cells significantly reduced cell proliferation and retarded GC tumour growth, whereas overexpression of PHB2 further enhanced GC cell proliferation." (PMID 38200519, 2024). "Our results demonstrated that the expression of myr-Akt effectively restored tumour growth, accompanied by Akt reactivation in mouse xenografts carrying sh-PHB2." (PMID 38200519, 2024). "Prohibitins, PHB1 and PHB2, function as tumor suppressors in head and neck squamous cell carcinomas." (PMID 37190120, 2023). "We then identified a nanobody enriched from dendritic cells (DCs) that targets Prohibitin-2 (PHB2) in the tumor and draining lymph nodes." (PMID 37978291, 2023). "A recent discovery disclosed the tumor proliferative function of PHB2 through its interaction with the oncogene Hes1." (PMID 37190120, 2023). "As we discussed in Section 3 and Section 4, PHB2 demonstrates both a tumor repressing function and an oncogenic function." (PMID 37190120, 2023). "We revealed the interaction between LacRNA and a known tumor suppressor, PHB2, which mediates the stability of the PHB2 protein." (PMID 36782197, 2023). "Subsequently, we detected the expression of PHB2 and Ki67 in tumor tissue sections by western blot and IHC assays, respectively." (PMID 36658121, 2023). "We further discovered that TPP-SS-ATS-LS inhibited tumor cells proliferation through mitophagy by regulating PHB2 and PINK1 expression." (PMID 35964052, 2022). "They argued that PHB2 knockdown suppresses cell growth and colony formation, leads to G1 phase arrest, sensitizes tumor cells to apoptosis, and inhibits the ability of tumor cells to adapt to hypoxic microenvironments." (PMID 33537079, 2021). "PHB2 was found to be overexpressed in NSCLC tumor tissues, and its expression was correlated with clinicopathological features." (PMID 33537079, 2021). "A549 and H1299 cells with endogenous PHB2 depletion were subcutaneously injected into nude mice, and xenograft tumor growth was monitored periodically." (PMID 33537079, 2021). "These achievements highlight the excellent therapeutic benefits achieved through reactivation of the tumor suppressor PHB2 and suggest the possibility of new therapeutics that will replace conventional endocrine therapeutics targeting E2 signaling." (PMID 34285339, 2021). "We found that PHB2 is overexpressed in NSCLC tumor tissues compared to normal controls and that its expression is correlated with clinicopathological features." (PMID 33537079, 2021). "As expected, we found that PHB2 knockdown led to a marked decrease in xenograft tumor volume and tumor weight." (PMID 33537079, 2021).
tumor (continued). "Consistent with this, PHB1 and PHB2 were recently shown to be overexpressed in lymphoid and myeloid tumor cell lines compared to normal naive and activated primary human PBMCs." (PMID 31684984, 2019). "In conclusion, for the first time our study identified a unique localization for PHB2 in RD and other tumor cells, which further deepens our understanding of this conserved protein and highlights the significance of its function." (PMID 29367618, 2018). "PHB2 was also shown to promote hepatocellular carcinoma growth and malignancy progression in the hypoxic tumor microenvironment." (PMID 29784973, 2018). "Although there was no statistical difference in DMFS between PHB2 high expressed and PHB2 low expressed ESCC tumor tissues (P = 0.248), high levels of PHB2 expression were correlated with OS in univariate analysis (P = 0.032)." (PMID 29683265, 2018). "Immunohistochemistry staining showed PHB2 expression in the tumor tissues of ESCC patients was significantly higher than the adjacent normal tissues." (PMID 29683265, 2018). "The functional role of PHB1 and PHB2 in tumorigenesis and the mechanism involved requires further investigation for potential implication of prohibitin domain family proteins in tumor diagnosis and treatment." (PMID 29784973, 2018). "Treatment with stERAP-6 every 4 days also led to the E2-dependent nuclear translocation of cytoplasmic PHB2 in tumours." (PMID 28500289, 2017). "The enhancement of PKA activity by E2 stimulation leads to the phosphorylation of BIG3 and suppresses the inhibition of PP1Cα activity, resulting in the dephosphorylation and inactivation of PHB2, which is essential for tumour suppressor activity." (PMID 28555617, 2017). "Compared to naive primary human PBMCs, PHB1 and PHB2 protein levels were 4.3 to 18.4 and 3.6 to 18.4 fold higher (p < 0.05) in the tumor cell lines, respectively." (PMID 29029444, 2017). "Densitometric analysis indicated that PHB1 and PHB2 were overexpressed (> 1 fold) in 61% and 79% of tumor samples, respectively compared to normal donor PBMCs." (PMID 29029444, 2017). "Taken together, PHB1 and PHB2 proteins are overexpressed in lymphoid and myeloid tumor cell lines compared to normal naïve and activated primary human PBMCs." (PMID 29029444, 2017). "Strong positive expression of PHB1 and PHB2 (100%; score 2 or score 3) was observed in the cytoplasm of tumor cells in all NASH HCCs." (PMID 28218651, 2017). "Phosphomimetic PHB2 mutants (Y34E/Y77E) exacerbate these effects, whereas phosphorylation-resistant mutants (Y34F/Y77F) restore cristae integrity, normalize redox balance, and suppress tumor progression." (PMID 41666677, 2026). "Furthermore, PHB2 has been shown to increase Cyclin A and Cyclin B expression, accelerating S/G2 phase progression and mitotic entry, thereby supporting rapid tumor growth and therapy resistance." (PMID 40076502, 2025). "PHB2 regulates cell cycle progression by modulating cyclin expression: its upregulation enhances Cyclin D1 and Cyclin E (G1/S transition) and Cyclin A and Cyclin B (S/G2 progression), driving tumor growth." (PMID 40076502, 2025). "Moreover, most studies have mainly focused on understanding how PHB1 affects tumours, leaving fewer investigations into the effects of PHB2, especially in GC." (PMID 38200519, 2024). "In the xenograft mouse model using HT-29 cells, knockdown of PHB2 retarded the tumor growth of CRC." (PMID 36658121, 2023). "Additionally, PHB2 had high expression levels in ESCC tumor tissues, which correlated with an overall worse survival." (PMID 37190120, 2023). "Pro-apoptotic cytc and anti-tumor phb and phb2 were significantly down-regulated." (PMID 37868974, 2023). "In a similar way, we hypothesize that targeting PHB2 by autoantibodies disrupts its role as tumor suppressor." (PMID 37082114, 2022).
tumor (continued). "Further studies on anti-tumor mechanisms have shown that the novel nano-preparation inhibits tumor cell proliferation through the mitochondrial autophagy pathway, which is mediated by down-regulating PHB2 and PINK1 expression." (PMID 35964052, 2022). "The results indicated that overexpression of fragment 1 could significantly inhibit tumor growth, reduce PHB2 and Ki67 expression, and increase the proportion of senescent cells in tumor tissues." (PMID 33754036, 2021). "Thus, in the present study, we determined the clinical relevance of PHB1 and PHB2 in 82 DLBCL tumor samples and show their potential importance in DLBCL cell survival and proliferation." (PMID 31684984, 2019). "In fact, loss of PHB2 is strongly associated with accelerated OPA1 processing, as well as impaired cell proliferation and apoptosis while an over-expression of PHBs is reported to protect cells from apoptosis, and it was found in several tumor cells." (PMID 31547300, 2019). "In order to meet the criterion of genetic engineering drugs, overcoming antigenicity against human and removing the His-tag from rLm-PHB2 would provide the opportunity for the application of rLm-PHB2 as a potential anti-tumor drug in the future clinical studies." (PMID 29500418, 2018). "In conclusion, these observations indicate that PHB1 and PHB2 activity contribute to tumor cell survival in the context of mitochondrial protection and therefore strengthen the potential value of these proteins as therapeutic targets in the treatment hematologic cancers." (PMID 29029444, 2017). "Taken together, these findings support the role of PHB1 and PHB2 in hematologic tumor cells for maintenance of mitochondrial integrity, which may facilitate the energy requirements of these tumor cells." (PMID 29029444, 2017). "In an effort to gain insight into the prohibitin molecular mechanism of action in lymphoid and myeloid-derived malignancies, PHB1 and PHB2 were determined to be overexpressed in tumor cell lines compared to normal primary human PBMCs and localized primarily to the mitochondria in Kit225 cells." (PMID 29029444, 2017). "While upregulation of PHB2 might inhibit tumor growth in ER-positive tumors, the biological consequences of upregulation in ER-negative breast cancer are unknown." (PMID 25004928, 2014). "As reviewed earlier in proteins of the TGN, GOLPH3 was shown to recruit prohibitin-2 and LC3-II to promote autophagy and tumour progression." (PMID 40293576, 2025). "PHB2 increases RACK1 expression through posttranslational modification and induces the activation of downstream tumor-promoting effectors." (PMID 37190120, 2023). "Through the pilot study on the antitumor mechanism, we found that TPP-SS-ATS-LS inhibit tumor cell proliferation through PINK1 dependent mitophagy, which was mediated by down-regulating the expression of PHB2." (PMID 35964052, 2022). "Our major finding in the present study is that PHB2 facilitates tumorigenesis in NSCLC by interacting and stabilizing RACK1, which further induces changes in downstream tumor effectors and pathways." (PMID 33537079, 2021). "Comparison of PHB and PHB2 expression in paired HCC tumor and corresponding non-tumor liver tissue of the TCGA-LIHC cohort revealed highly significant overexpression of PHB (fold-difference = 1.78; p < 0.001) but not PHB2 (N = 50)." (PMID 33257655, 2020). "We found that PHB2 expression was related to the OS of ESCC patients and had high levels in the tumor tissues and human cell lines of ESCC." (PMID 29683265, 2018). "We subsequently investigated expression of PRDX1, FMNL, NCL, CLIC3, FLNA, PHB2, and FABP5 of 229 ESCC tumor tissues by TMA." (PMID 29683265, 2018). "PHB2 expression was related to the OS of ESCC patients (P = 0.032) and had high levels in the tumor tissues and human cell lines of ESCC (P = 0.0002)." (PMID 29683265, 2018).
tumor (continued). "Given its role in cell cycle regulation (Cyclin D1, Cyclin E) and mitochondrial stress responses, PHB2 may influence the efficacy of TMZ and other chemotherapeutic agents by modulating tumor metabolism and oxidative stress responses." (PMID 40076502, 2025). "Furthermore, our clinical samples revealed that elevated PHB2 expression correlates with reduced SHIP2 protein levels, subsequently resulting in the activation of Akt in GC patient tumour tissues in comparison with adjacent normal tissues." (PMID 38200519, 2024). "To further explore whether PHB2 promotes tumor progression by regulating RACK1, we depleted endogenous RACK1 in PHB2-overexpressing A549 cells." (PMID 33537079, 2021). "The expression of PHB2 was not correlated with other clinical factors such as age, gender, tumor differentiation, T/N status and postoperative chemotherapy." (PMID 29683265, 2018). "We determined the PHB2 mRNA and protein levels in 90 pairs of ESCC tumor tissues and their adjacent normal tissues, and the results indicated that PHB2 expression was extremely significantly higher in the ESCC tumor tissues than the adjacent normal tissues." (PMID 29683265, 2018). "Results indicated that tumor tissues of ESCC patients with metastasis had higher PHB2 expression level than the nonmetastasis patients, and ESCC patients with high PHB2 expression had higher metastasis rate than ESCC patients with low PHB2 expression after surgery." (PMID 29683265, 2018). "This discrepancy may reflect the fact that the PKCα targeting of PHB2 for tumour suppression may be non-functional by PKA–BIG3–PP1Cα complex, thereby inducing an apparent ‘loss-of-function’ of the PHB2 protein." (PMID 28555617, 2017). "Third, Rocaglamide A, a member of the flavagline class of compounds, binds to both PHB1 and PHB2 at the cell membrane to inhibit Raf activation and Raf-MEK-ERK-mediated cell cycle progression and cell proliferation in tumor cell lines, without inducing mitochondrial fragmentation." (PMID 26497683, 2015).
infection (19 papers, 2012 to 2026). The state of being infected such as from the introduction of a foreign agent such as serum, vaccine, antigenic substance or organism. "Located in phospholipid-rich subcellular sites such as the plasma membrane and mitochondrial inner membrane, PHB1 and PHB2 are emerging as important host targets for bacteria and viruses, influencing infection and host responses by these microbes." (PMID 42311502, 2026). "Verified in this experiment, PA14 infection of C. elegans triggers stress and immune responses, accompanied by upregulated expression levels of phb-1 and phb-2." (PMID 41409596, 2025). "In turn, prohibitin 2 directed EVA71 infection (intracellular EVA71 RNA and supernatants viral titers) in a manner partly dependent on the acidification of autolysosomes, which is involved in the complete autophagy induction." (PMID 33298183, 2020). "According to immunofluorescence assays, the VP1 and PHB2 proteins colocalized at various time points after infection." (PMID 32276428, 2020). "The present study identified, for the first time in comparative medicine, that the IMM protein PHB2 is a receptor involved in parkin-mediated mitophagy in urothelial cells from cattle suffering from a spontaneous infection by BPVs." (PMID 32751272, 2020). "Prohibitin 2 directs EVA71 infection (intracellular EVA71 RNA and supernatants viral titers) as partially dependent on the acidification of autolysosomes." (PMID 33298183, 2020). "In conclusion, we found that the host protein PHB2 is involved in EV-A71 infection and enhances the autophagy mechanism during EV-A71 infection." (PMID 32276428, 2020). "In the infection process, GDAP would trigger apoptosis to inhibit BmNPV infection, while PHB2, CRT, RCX1 and HSP60 had the opposite effects." (PMID 25502928, 2014). "While Phb2 knock down reproducibly favored the infection by both strains of TMEV, it failed to significantly affect MuHV-4 infection and even inhibited VSV infection." (PMID 26196674, 2015). "Knocking down Phb2 and, to a lesser extent, Phb1 expression in cells that overexpressed Apol9 significantly enhanced but did not fully restore infection." (PMID 26196674, 2015). "PHB2 may interact with EV-A71 VP1 to regulate autophagy, thus affecting EV-A71 infection." (PMID 32276428, 2020). "Accordingly, rather than by directly binding to LC3, PHB2 may regulate autophagy during EV-A71 infection through mechanisms that need further investigation." (PMID 32276428, 2020). "Interestingly, knocking down Phb2 also increased infection by TMEV in cells that did not overexpress Apol9, suggesting that this prohibitin has antiviral activity per se, against TMEV." (PMID 26196674, 2015). "Furthermore, PHB2 co-precipitated ERAS more appreciably in cells from bladder mucosa infected by BPVs rather than in cells from healthy mucosa, which suggested that this functional stochiometric complex was upregulated in activated mitophagy upon BPV infection." (PMID 32751272, 2020).
neurodegenerative disease (4 papers, 2022 to 2025). A disorder of the central nervous system characterized by gradual and progressive loss of neural tissue and neurologic function. "Furthermore, in rodent studies, mice with neuron‐specific PHB2 deficiency exhibited neurodegenerative disease with a reduced lifespan that could be rescued by additional ablation of Oma1." (PMID 41388823, 2025). "Phb2 deletion specifically in forebrain neurons results in neurodegenerative disease and premature death in mice." (PMID 36593241, 2023).
cardiovascular diseases (2 papers, 2023 to 2024). "Prohibitin 2 (PHB2) and phosphoglycerate mutase 5 (Pgam5) have been associated with altered mitochondrial homeostasis in several cardiovascular diseases; however, their role in endotoxemia-related myocardial dysfunction has not been explored." (PMID 37781037, 2023).
kidney disease (2 papers, 2015 to 2025). "To better understand the beneficial effect of podocyte-specific insulin signaling deficiency for renal disease and the role of PHB2 on metabolic signaling in podocytes, we next generated a Phb2 knockdown podocyte cell culture model." (PMID 25643582, 2015). "To understand the contribution of mitochondrial dysfunction to kidney disease, we generated podocyte-specific Phb2 knockout mice." (PMID 25643582, 2015). "To understand the contribution of mitochondrial dysfunction to kidney disease, we deleted the Phb2 gene specifically in podocytes (Phb2pko) by mating a conditional Phb2fl/fl mouse line to podocyte-specific Cre mice (NPHS2.cre)." (PMID 25643582, 2015).
metabolic disease (2 papers, 2021 to 2025). A congenital disorder (due to inherited enzyme abnormality) or acquired (due to failure of a metabolically important organ) disorder resulting from an abnormal metabolic process. "Dysfunctions of PHB1/PHB2 are known to be associated with podocyte cytotoxicity, oxidative stress, and metabolic diseases." (PMID 40168274, 2025).
bacterial infections (1 paper, 2025). "Future endeavors aimed at unraveling the molecular interactions involving ATG5, PINK1, Parkin, and PHB2, combined with more comprehensive functional assays, hold the potential to provide insights into the intricate role of ATG5 in mitophagy, particularly in the context of bacterial infections." (PMID 40529614, 2025).
hematologic malignancies (1 paper, 2017). "Subsequently, siRNA-mediated knockdown of PHB1 and PHB2 in Kit225 cells significantly enhanced sensitivity to H2O2-induced cell death, suggesting a protective or anti-apoptotic function in hematologic malignancies." (PMID 29029444, 2017).